CXCR5 (C-X-C motif chemokine receptor 5)
Diseases named in the same sentence as CXCR5 in open-access papers (continued):
Sharing a sentence is not in itself a finding about the gene and the disease.
Uterine leiomyoma (1 paper, 2019). The presence of a leiomyoma of the uterus. "Given regulatory T (Treg; CD4+CD25+CD127−), helper T (Th; CD3+CD4+CXCR5−), and follicular helper T (Tfh; CD3+CD4+CXCR5+) cells are all differentiated from the naïve CD4+ T cells, we further compared the distribution of these cells between patients with uterine leiomyoma and healthy controls." (PMID 31772580, 2019).
tumor (235 papers, 2008 to 2026). "IFNG and CXCR5 were significantly associated with tumor size (p = 0.032 and p = 0.047, respectively), and their expression was lower in invading tumors (T4)." (PMID 38831317, 2024). "Consistently, we found significant associations between lower expression of IFNG, CD40LG, and CXCR5 and larger tumor sizes or adjacent tissue invasion (p = 0.01, p = 0.03 and p = 0.01, respectively)." (PMID 38831317, 2024). "These cell suspensions contained malignant CD4 + Thf-like cells, which express PD1 and CXCR5, and the associated tumor microenvironment consisting of germinal center (GC) B cells and CD8 TILs." (PMID 39272178, 2024). "In the TCGA BRCA dataset, similarly, the authors have demonstrated significant associations between lower expression of IFNG, CD40LG, and CXCR5 and larger tumor sizes or adjacent tissue invasion (p = 0.01, p = 0.03, and p = 0.01, respectively)." (PMID 39001456, 2024). "Further analyses showed that the expression of IFNG and CXCR5 were significantly associated with tumor size (p = 0.032 and p = 0.047, respectively), and their expression was lower in invading tumors (T4)." (PMID 39001456, 2024). "Briefly, chemokine expression on tumor cells was associated with poor outcomes, whereas CXCR5 expression on TILs was found to be a good prognostic factor in the present cohort." (PMID 39001456, 2024). "CXCL13/CXCR5-associated immune processes are fundamentally involved in anti-tumor defense, and the effector cells of the axis are all but irrelevant side-targets of anti-PD-1 therapy." (PMID 36836910, 2023). "Cancer-associated fibroblasts secrete CXCL13 to recruit CXCR5+ B cells expressing lymphotoxin-α1β2, which expands TLSs in the tumor microenvironment." (PMID 35053457, 2022). "For example, in gastric cancer, the accumulation of CXCR5+ CD8 T cells in the tumor is associated with better patient overall survival (OS)." (PMID 36172358, 2022). "We summarize the previous findings examining the association between CXCL13/CXCR5 expression and the clinical response to tumor immunotherapy." (PMID 35053457, 2022). "We envisage that eliminating a large tumor mass by our CXCR5 CAR-T cells is of higher therapeutic benefit than the loss of a minor tumor-infiltrating CD8+CXCR5+ T cell population." (PMID 33431832, 2021). "For example, CXCL13 interacts with the chemokine receptor CXCR5 which is present on B cells and some tumor cells and has been implicated as key modulators of both tumor progression and antitumor immunity." (PMID 33193299, 2020). "NKp46+CCR6+CXCR5+ ILC3s with LTi properties are also enriched in tumor-associated tertiary lymphoid structures in human non-small cell lung cancer." (PMID 31507605, 2019). "Multivariate analyses revealed that age, tumor stage, and CXCR5 expression were independent risk factors for OS." (PMID 31781492, 2019). "Furthermore, CXCR5, primarily expressed in B-cells, has been shown to mediate B-cell homing to tumor sites, where it can contribute to tumor-associated inflammation and immune evasion." (PMID 41024311, 2025). "Furthermore, CXCL13 expression is closely associated with the recruitment of CXCR5+ immune cells to tumor sites, directing and positioning them within lymphoid follicles, particularly CXCR5+ B cells." (PMID 41374956, 2025). "The CXCL13/CXCR5 axis is associated with tumor development, proliferation, and invasion." (PMID 37503314, 2023). "The CXCL13/CXCR5 axis is linked with tumor development, progression, proliferation, and invasion." (PMID 35053457, 2022). "Only CXCR5 expression level was associated with tumor staging." (PMID 33829065, 2021). "Activation of the CXCR1/CXCR2 pathway and the CXCR4/CXCR7 pathway is associated with tumor aggressiveness and poor prognosis; the CXCR3 and CXCR5 axes play a role in tumor suppression; and common variants encoding the CXC chemokine gene have also been studied as biomarkers of CRC." (PMID 32774427, 2020).
tumor (continued). "Interestingly, the top up-regulated genes encode proteins involved in tumor progression (Cxcr5 and Aicda), while the top down-regulated genes are strong tumor inhibitors (Anxa10 and Expi)." (PMID 30123421, 2018). "CXCL12 (SDF-1) and CXCL13 (BLC) and their respective receptors CXCR4 and CXCR5 have been implicated in tumor growth, metastasis, and are critical for the regulation of the tumor microenvironment in multiple cancer sub-types as a component of the tumor “Immunome”." (PMID 24795716, 2014). "Furthermore, when colon cancer cells were endoscopically injected into the colon submucosa, CXCL13 injection reduced tumor formation, whereas the deficiency in CXCR5 gene, a receptor for CXCL13, accentuated tumor formation." (PMID 24966464, 2014). "To evaluate whether patients with CXCR5+CD8+T-high tumor might benefit more from ACT (±RT) compared with patients with CXCR5+CD8+T-low tumor, we investigated the association between CXCR5+CD8+T cells density and OS among patients with TNM II + III diseases who either did or did not receive ACT." (PMID 34035252, 2021). "Alternatively, the infiltration of CAR-T cells into the tumor is being improved by expressing the C-X-C chemokine receptor type 5 (CXCR5)." (PMID 39995659, 2025). "Naïve B cells mediate the activation of EF pathway B cells under the auxiliary stimulation of PD-1hiCXCL13+CXCR5- Tph from the T-cell area and tumor antigen complexes presented by FDCs." (PMID 39744696, 2025). "The chemokine receptors CCR6, CCR7, CXCR3, CXCR4, CXCR5, and CXCR6 have the highest expression across lymphocytes, and CCR8, a known hallmark of tumour infiltrating Treg cells, is exclusively expressed on Treg cells." (PMID 39915477, 2025). "Another signature chemokine (CXCL13) and its receptor (CXCR5) were detected in B cell-rich zones of tumor/TLS sections." (PMID 39827246, 2025). "Elevated CXCL13 secretion, in turn, enhances tumor growth, migration, and invasion through CXCR5 on the tumor cell surface." (PMID 40406143, 2025). "The interaction between T follicular helper cells and B cells can promote immune-activated germinal center response, which further activates CCL19-21/CCR7 axis and CXCL13/CXCR5 axis and promotes tumor development 50-52." (PMID 39895788, 2025). "The exploratory study indicated a higher infiltration of CD4+/CD8+ CXCR5+ T follicle helper cells, CD8+CD103+ tissue-resident memory T cells, and B cells in tumor tissue, associated with better response and prognosis." (PMID 40404633, 2025). "Those anti-tumor effects are mainly caused by the pathways of B cells, such as CCL19, -21/CCR7 axis and CXCL13/CXCR5 axis." (PMID 40158161, 2025). "Previous studies have shown that the CXCL13/CXCR5 axis contributes to tumor growth, proliferation, metastasis, and invasion." (PMID 40649942, 2025). "The HER2-CXCR5-CCR6-CAR T group demonstrated the most effective control over orthotopic HCC827-Luciferase tumors, with a final tumor bioluminescence photon flux of 14,600 ± 5,313.67 p/s, highlighting the synergistic benefits of CXCR5 and CCR6 co-expression." (PMID 40764989, 2025). "The results of in vivo CAR-T tracking experiments showed that CAR-T cells modified with CXCR5 can migrate and infiltrate toward tumor lesions in a targeted manner, significantly clearing the tumor while greatly reducing potential extratumoral toxicity." (PMID 40469307, 2025). "CXCL13, in combination with anti-PD-1 therapy, retarded tumor growth in vivo, resulting in increased infiltration of CXCR5+CD8+ T cells." (PMID 40406143, 2025). "Preclinical models have demonstrated that the CXCL13/CXCR5 axis is crucial for promoting intra-tumour T-cell migration, and accordingly, tumours with high CXCL13 expression exhibit an increased infiltration of activated CD8+ CXCR5+ T-cells." (PMID 40361472, 2025). "Lower CXCR5 in tumour B cells and Tfh T cells in ME patients will likely impact the effectiveness of B cell migration, retention and responses within the tumour site." (PMID 39915477, 2025).
tumor (continued). "T follicular helper cells regulate tumor growth and progression through the chemokine receptor CXCR5." (PMID 39771050, 2024). "CD8+ CXCR5+ cells were significantly enriched in peripheral tumor tissues compared with circulating T cells." (PMID 38335302, 2024). "The principal accessory cell of TIL-B is closely linked to Tfh TIL, identified by expression of CXCR5, a marker known for its role in anti-tumour immune responses within TLS across various tumour types." (PMID 38582847, 2024). "Expression of CXCR4 and CCR5 on tumor was found to be associated with poor prognosis in this cohort with TNBC, and CXCR5 on tumor was associated with chemotherapy resistance." (PMID 39001456, 2024). "This is why CAR-T cells co-expressing CXCR5 were superior to conventional CAR-T cells in eradicating ligand-positive tumor cells." (PMID 39450160, 2024). "As a chemoattractant, CXCL13 facilitates the formation of TLS and plays an important role in anti-tumor activity through the CXCL13/CXCR5 axis and T follicular helper cells." (PMID 39544934, 2024). "Resembling human AITL disease, mAITL CD4+ tumor cells are indeed positive for Tfh markers (PD-1, CXCR5)." (PMID 38897995, 2024). "Closely resembling human AITL disease, murine CD4+ tumor cells expressed Tfh markers (PD-1, CXCR5) as their human counterparts, which are often defined as Tfh-like cells." (PMID 38321568, 2024). "We also found that the median proportion of CXCR5+ CD8+ T cells in peripheral tissues was higher than that in central tumor tissues, and that CXCR5+ cells had higher levels of PD-1 than CXCR5− T cells." (PMID 38335302, 2024). "The CXCL13/CXCR5 axis has been identified as a key mediator of pro-tumorigenic immune responses, facilitating the recruitment of immunosuppressive cells to tumor sites." (PMID 39835121, 2024). "CXCL13, a ligand of the CXCR5 receptor, is a chemotactic protein for B cells that recruits CXCR5+ B cells to tumor tissues, thereby enhancing tumor immunity." (PMID 39611128, 2024). "CXCR4 and CXCR5 were also more highly expressed in tumor-rich tissues than in circulating T cells, but only in CD8+ T cells." (PMID 38335302, 2024). "The overexpression of CXCR5 was accompanied by a remarkable increase in the proliferation and migration of the tumor cells." (PMID 37159817, 2023). "This review summarizes our current understanding of the CXCR5/CXCL13 immune axis, its role in TLS formation within cancer tissue and the associated tumor microenvironment (TME), and its influence on anti-tumor immune defenses." (PMID 36836910, 2023). "The CXCL13/CXCR5 axis is crucial for intra-tumor T-cell migration, and accordingly, tumors with high CXCL13 expression exhibit an increased infiltration of activated CD8+ CXCR5+ T cells." (PMID 37898752, 2023). "It is widely recognized that immune effector cells expressing PD-1 migrate from the blood to the sites of immune priming in secondary lymphoid organs or tumor microenvironment via CXCR5/CXCL13, in which they become resident cells." (PMID 37691941, 2023). "High CXCL13 levels, in turn, lead to the recruitment of CXCR5-positive Tfh and B cells to, and their aggregation in, the tumor site." (PMID 36836910, 2023). "It has been found that peripheral CD4+CXCR5+ T cells participate in the pathogenesis and progress of OS, and patients with high tumor grade show a significant increase in the percentage of CD4+CXCR5+ T cells compared with patients with low OS grade." (PMID 37064862, 2023). "Upon entry into the circulation, tumour cells will quickly encounter platelets and granulocytes, and the release of platelet-derived chemokines CXCR5/7 from tumour-bound platelets actively recruits granulocytes to platelet-tumour aggregates." (PMID 38106409, 2023). "The enhanced interactions between CD20+CXCR5+ B cells and Treg cells suggested that B cells in peritumoral IH were subjected to stronger regulation, potentially due to the accumulation of tumor-specific autoantibodies in peritumoral IH." (PMID 36853169, 2023).
tumor (continued). "It has been demonstrated that anti-viral and anti-tumor immunity after PD-1/PD-L1 checkpoint blockade is mediated by the proliferative burst of TCFI+CXCR5+ cells." (PMID 37691941, 2023). "With sequencing techniques advancing, teasing out the implications of protein antigens from tumor proteins or self-proteins would delineate if CXCR5+CD8 T cells pose a threat to the development of IMAEs." (PMID 36314014, 2022). "CXCL13 and the receptor CXCR5 represent an emerging example of a chemokine signaling axis that demonstrates the ability to regulate tumor growth and progression." (PMID 35770088, 2022). "The CXCL13/CXCR5 axis is activated by the interaction of B cells and Tfh cells to accelerate the GC reaction; it participates in the migration of tumor B cells and Tfh cells in the TME." (PMID 34689225, 2022). "CXCR5+CD8 T cells from human peripheral blood mononuclear cells, tumor tissues and tumor associated lymph nodes upregulate effector molecules such as IFNγ, TNFα, granzyme B, and perforin compared to CXCR5−CD8 T cells." (PMID 36314014, 2022). "In control, autocrine chemokine ligand 13 (CXCL13)-C-X-C chemokine receptor type 5 (CXCR5) axis promoted tumor development and progression in HCC and TNBC." (PMID 35392977, 2022). "The CXCL13/CXCR5 axis is confirmed to facilitate tumor cell growth and metastasis in prostate cancer and colorectal cancer via MAPK and PI3K/AKT signaling pathways." (PMID 36612163, 2022). "It specifically binds to the corresponding receptor CXCR5, directly regulating tumor progression or indirectly modulating adaptive immune responses." (PMID 35570844, 2022). "As with most areas of cancer research heterogeneity between cancer types, biomarkers, and tumor microenvironments creates cumbersome and often contrasting phenotypic conclusions regarding CXCR5+CD8 T cell functions." (PMID 36314014, 2022). "When the cancer microenvironment is enriched in CXCL13, the recruitment of CXCR5-expressing leukocytes to the tumor microenvironment increases." (PMID 35053457, 2022). "In our study, CXCL13/CXCR5 axis interacts with PD-1/PD-L1 inhibitory signal and acts a double-edged sword in tumor progression and response to immunotherapy." (PMID 35392977, 2022). "In patients treated with ICB, high CXCL13 expression leads to more favorable tumor outcomes perhaps due to CXCR5+CD8 T cells expanding the effector T cell pool or as a consequence of these cells increasing proliferation while resisting apoptosis." (PMID 36314014, 2022). "This review discusses how CXCL13/CXCR5 signaling modulates cancer and immune cells to promote lymphocyte infiltration, activation by tumor antigens, and differentiation to increase the antitumor immune response." (PMID 35053457, 2022). "We identified follicular B cells expressing high levels of CD20 (MS4A1) and CXCR5 in both tumor (cluster 5) and adjacent normal kidneys (clusters 1)." (PMID 36028490, 2022). "At the moment, various novel approaches are being employed to inhibit CXCL13/CXCR5 signaling in the tumor microenvironment and our study is in line and further support this effort by providing additional valuable information." (PMID 36217194, 2022). "BTKi modulate the TME and tumor B-cell interaction, leading to a redistribution of lymphocytosis caused by inhibition of signaling and function of chemokine receptors (CXCR4, CXCR5) and adhesion molecules." (PMID 35804999, 2022). "To explore the mechanism underlined the preceding observations, we therefore investigated the features of CXCR5+CD8+T presented in tumor tissues by using the fresh surgical specimens of GC." (PMID 34035252, 2021). "So far, CXCL13 and its related receptor CXCR5 have been proved to regulate cancer cell migration as well as tumour metastasis." (PMID 34427969, 2021). "Patients with TNM II + III disease whose tumor with higher CXCR5+CD8+T have superior OS benefit from ACT (±RT)." (PMID 34035252, 2021).